TNF (tumor necrosis factor)
Diseases named in the same sentence as TNF in open-access papers (continued):
Sharing a sentence is not in itself a finding about the gene and the disease.
endometriosis (continued). "Although pharmacological interventions targeting cytokines have not undergone analysis in clinical trials, epidemiological data concerning the efficacy of various inhibitors of TNFα and IL-1β concerning endometriosis and fertility must be examined." (PMID 40508002, 2025). "CD14 helps LPS recognize and activate TLR4, triggering the MyD88/NF-κB pathway, which promotes the release of IL-1, IL-6, and TNF-α, thus initiating systemic inflammatory cascades that contribute to the occurrence and progression of endometriosis." (PMID 40692689, 2025). "Some studies demonstrated that proinflammatory cytokines such as IL-6, IL-8, and TNF-α participate in the pathogenesis of endometriosis." (PMID 40507929, 2025). "Several cytokines, including vascular endothelial growth factor (VEGF), interleukin 6 (IL-6), and tumor necrosis factor α (TNF-α), have been studied in the pathogenesis of endometriosis." (PMID 39859551, 2025). "Endometriosis is characterised by elevated levels of pro-inflammatory factors such as interleukin 6 and 8 (IL-6/IL-8), tumour necrosis factor alpha (TNF-α), and prostaglandin E2 (PGE2)." (PMID 41303437, 2025). "This suggests that the dysregulated expression of VEGF, TNF‐α, and IL‐6 contributes to the abnormal angiogenic processes observed in endometriosis." (PMID 39803270, 2025). "In endometriosis, for example, an excess of pro-inflammatory cytokines like TNF-α, IL-1β, and IL-6 leads to chronic inflammation and the formation of lesions outside the uterus, this can impair fertility." (PMID 41377340, 2025). "In the context of endometriosis, C5a stimulates peritoneal macrophages to produce pro-inflammatory cytokines IL-1β, IL-6, TNF-α, and IL-8, enhancing the cytokine imbalance characteristic of this disease (Section 4)." (PMID 41488658, 2025). "In mice, the EZH2 inhibitor GSK343 reduced TNFα levels and endometriosis progression, similar to gene knockdown of ERβ or EZH2." (PMID 40630095, 2025). "It has also been suggested that TNF-α is responsible for peritoneal fluid-mediated enhancement of eutopic and ectopic endometrial cell proliferation in women with endometriosis." (PMID 40507929, 2025). "The reduced percentages of CD56 + NKp45 + and CD56dimNKp46 + NK cells were related to the reduced cytotoxicity of the pfNK cells in endometriosis, and the secretion of TNF-α and IFN-γ were increased." (PMID 40679648, 2025). "Patients with endometriosis show elevated concentrations in peritoneal fluid of key cytokines supporting cell-mediated immunity and inflammation: IL-1β, IL-6, and TNF-α." (PMID 41488658, 2025). "One study has focused on oxidative stress biomarkers and the subsequent impact on cardiovascular risk in endometriosis patients, such as elevated levels of pro-inflammatory cytokines like thymic stromal lymphopoietin (TSLP), TNF-α, and IL-1β." (PMID 40564779, 2025). "In women with endometriosis and infertility, an imbalance in the intestinal microbiota leads to a substantial increase in TNF-α levels in the peritoneal fluid, exacerbating the inflammatory environment and contributing to reproductive dysfunction." (PMID 40692689, 2025). "Research has shown increased levels of IL-1β, IL-6, and TNF-α in tissues affected by endometriosis, which confirms the crucial role of these cytokines in the disease’s pathophysiology." (PMID 40725782, 2025). "The EZH2 inhibitor GSK343 was shown to suppress TNFα expression and endometriosis development in a mouse model." (PMID 40630095, 2025). "Given the elevated TNF-α levels in EPF, the addition of soluble TNF-α receptor 1 (sTNFR-1) partially rescued PRL secretion in eutopic (endometriosis) ESCs, suggesting that TNF-α mediates the inhibitory effects of EPF." (PMID 40072055, 2025). "BEVs can be formed from the microbiota in the endometrial fluid and can induce the secretion of TNF, IL-6, and IL-17, which are involved in endometriosis." (PMID 40508002, 2025).
endometriosis (continued). "Treatment for endometriosis must involve interventions that can modulate the multidimensional nature of the disease, which involves inflammatory (IL-6, TNF-α, CCL2), hormonal (ERβ, aromatase, 17β-estradiol) and oxidative (MDA, ROS, SOD/GPx) factors." (PMID 41303437, 2025). "The combination of CA-125 with IL-8 and TNF-α during the secretory phase of the menstrual cycle gives a sensitivity of 89.7% and specificity of 71.1% for endometriosis." (PMID 40507929, 2025). "Immunological Effects: Antibiotic therapy reduces pro-inflammatory cytokines, such as IL-6 and TNF-α, in CE and endometriosis, mitigating the chronic inflammatory environment that fosters lesion survival." (PMID 40725782, 2025). "None of the other investigated interleukins (IL-1β and IL-8) and TNF-α showed any differences in the serum of endometriosis patients in any comparison." (PMID 40724945, 2025). "High levels of pro-inflammatory cytokines, including IL-1, -6, -8, 33, NF-kB, and tumor necrosis factor-alpha (TNF-α), have been well documented in several endometriosis developmental stages." (PMID 41170181, 2025). "Normally, TNF-α induces apoptosis; however, in the endometriosis context, ectopic cell sensitivity to TNF-α proapoptotic effects is reduced." (PMID 41488658, 2025). "Elevated levels of TNF-α in the abdominal fluid of women with endometriosis can negatively affect the gametes and fertilized eggs within the fallopian tubes, thereby compromising fertility." (PMID 40692689, 2025). "After the rats were euthanized, peritoneal lavage fluid was collected to assess tumour necrosis factor alpha (TNF-α) and interleukin 6 (IL-6), which are the most relevant to the pathogenesis of endometriosis." (PMID 41303437, 2025). "Monocytes in women with endometriosis tend to produce higher levels of pro-inflammatory cytokines such as TNF-α, IL-1β, and IL-6." (PMID 41377340, 2025). "IL6, a pro-inflammatory cytokine that has been reported to be highly expressed in ovarian endometriosis, dominated pathways of TNF signaling and NF-κB activation, which are hyperactive in endometriosis and implantation failure." (PMID 41227338, 2025). "This shift triggers TNFα upregulation, leading to oxidative stress, cell proliferation, inflammation, and ultimately promoting endometriosis progression." (PMID 40630095, 2025). "Prior studies have shown that peritoneal fluid from endometriosis patients contains elevated levels of pro‐inflammatory cytokines, such as IL‐6, IL‐8, and TNF‐α, as well as increased oxidative stress markers." (PMID 40922382, 2025). "For instance, TNF-α inhibitors, such as infliximab or adalimumab, are used in conditions involving chronic inflammation, and their application in reproductive disorders could help mitigate the inflammation associated with endometriosis and improve symptoms like pelvic pain and infertility." (PMID 41377340, 2025). "Research has also highlighted proangiogenic factors, such as VEGF, IL-1β, and TNF-α, which play a crucial role in the vascularization of endometriosis." (PMID 40508002, 2025). "Conversely, the EZH2 inhibitor GSK343 reduces EZH2-driven H3K27me3 modifications, thereby suppressing TNFα levels and impeding endometriosis development." (PMID 40630095, 2025). "This lack of responsiveness is further amplified by the chronic inflammatory state typical of endometriosis where cytokines such as IL-6 and TNF-α can work in tandem to elevate VEGF levels." (PMID 39982662, 2025). "This activation suppresses IL-6 and TNF-α, which are two pro-inflammatory cytokines prominently involved in endometriosis pathophysiology." (PMID 40430189, 2025). "The downregulation of miR-138 expression enhances inflammation in endometriosis by elevating levels of TNF-α, IL-1β, IL-6, and IL-18 through the activation of the NF-κB signaling pathway and VEGF." (PMID 39001478, 2024).
endometriosis (continued). "In endometriosis-dependent estrogen pathway, estrogen activates peritoneal macrophages to stimulate proinflammatory cytokines, including tumor necrosis factor (TNF) and interleukin-1β (IL-1β)." (PMID 38304042, 2024). "Autocrine and/or paracrine cytokines regulating local immune and inflammatory responses; expression of COX-2 in peritoneal macrophages influences the severity of endometriosis, dysmenorrhea, and infertility; central hyperexcitability from TNF-α." (PMID 39596309, 2024). "In endometriosis, macrophages and mast cells have been found to release chemokines such as TNF and IL-6." (PMID 39536051, 2024). "Regarding female infertility, patients with endometriosis with infertility presented higher concentrations of inflammatory markers IL-6, IL-10, IL-13, and TNF-α than controls." (PMID 38612425, 2024). "Elevated TyG index causes the immune system to produce extensive immune-inflammatory factors, such as TNF-α and IL-1, which promote the development of endometriosis." (PMID 39536051, 2024). "The heightened production of tumor necrosis factor, triggered by activated macrophages, along with the effect of IL-17 on endometrial cells, hastens the formation of endometriosis, often leading to unexplained pelvic pain and infertility." (PMID 39456936, 2024). "Endometriosis and cancer share a common inflammatory pathogenesis involving TNF-α, IL-1, IL-6, IL-8, and PGE2." (PMID 39458478, 2024). "Among the several immunomodulatory drugs approved for IBD, only the TNF-α antagonist infliximab has also been used for treating endometriosis, with disappointing results." (PMID 39595086, 2024). "Comparing data from three studies (256 patients), the sensitivity of TNF-α for diagnosing endometriosis ranged from 68% to 89%, while the specificity ranged from 35% to 87%." (PMID 39767772, 2024). "In endometriosis, the NF-κB pathway becomes activated, leading to the expression of pro-inflammatory genes and the production of cytokines such as TNF-α and IL-1β." (PMID 39229427, 2024). "The primary outcome was changes in pelvic pain as measured by the Endometriosis Symptoms Severity Scale 29 but were also analyzed Quality of Life outcomes and measurement of the serum concentrations of IL-6 and TNF." (PMID 38697213, 2024). "Immunomodulators, such as tumor necrosis factor-alpha (TNF-α) blockers, have shown promise in reducing endometriosis-associated pain and lesion size." (PMID 39229427, 2024). "Some of them are based on the increased production of pro-inflammatory cytokines recorded in women with endometriosis, such as IL-1, IL-6, IL-8, IL-33, TNF, or insulin-like growth factor 1 (ILGF-1)." (PMID 38999290, 2024). "This was evidenced by a significant reduction in TNF‐α levels within endometriosis lesions post‐treatment, thereby synergistically inhibiting the initiation and progression of endometriosis." (PMID 39373358, 2024). "NGF is a critical mediator of pain in endometriosis, often upregulated by inflammatory cytokines such as tumor necrosis factor-α (TNF-α) and interleukin-1β (IL-1β)." (PMID 39324359, 2024). "The inflammatory environment in endometriosis is characterized by an intricate balance between pro-inflammatory cytokines, such as IL-1, IL-6, and TNF-α, and anti-inflammatory cytokines, including IL-4, IL-10, and TGF-β." (PMID 39229427, 2024). "TNF-α and IL-1β mainly secreted by macrophages are highly expressed in the peritoneal fluid of endometriosis patients which can lead to peripheral nerve hypersensitivity and hyperalgesia." (PMID 38505548, 2024). "DII scores were assessed for the role of food on inflammatory biomarkers, such as IL-6, C-reactive protein, and TNF-a, all of which increased in endometriosis." (PMID 39683382, 2024). "Significant decreases in serum levels of IL-1β and TNFα were observed in women with endometriosis treated with ATX for 12 weeks." (PMID 39199150, 2024).
endometriosis (continued). "Proinflammatory cytokines, including IL such as IL-1, IL-8, IL-33, nuclear factor kappa B (NF-κB), and TNFα, have been widely documented during various stages of endometriosis progression." (PMID 38540637, 2024). "TNF-α in endometriosis has also been previously studied, but there has been insufficient evidence that anti-TNFα drugs are effective in treating pain symptoms in patients with endometriosis." (PMID 38972981, 2024). "Recently, we indicated that ASX significantly decreased serum levels of IL‐1β, IL‐6, and TNF‐α in endometriosis patients." (PMID 39479675, 2024). "Some studies have shown that endometriosis is a manifestation of pelvic inflammatory disease, with abundant inflammatory factors in the pathologic examination of endometriosis, such as IL-6, macrophage migration inhibitory factor, TNF-α, IL-1b, IL-6, and IL-8." (PMID 39536051, 2024). "Specifically, the levels of TNFα, IL-1β, and IL-6 are increased in peritoneal macrophages isolated from endometriosis patients." (PMID 39192982, 2024). "In fact, the TNF-α levels are significantly elevated in the peritoneal fluid of patients with endometriosis." (PMID 38785987, 2024). "TNF-α is a pleiotropic cytokine that plays an important role during the inflammatory process involved in the progression of endometriosis." (PMID 38892003, 2024). "A high consumption of trans fatty acids has been shown to increase proinflammatory markers such as Interleukin 6 (IL-6) and Tumor Necrosis Factor Alpha (TNF-α), involved in the pathogenesis of endometriosis." (PMID 39062050, 2024). "On the other hand, TNF-α is one of the most prominent cytokines that participate in endometriosis pathogenesis." (PMID 38785987, 2024). "The substantial involvement of inflammatory mediators and diverse cytokines, including TNF-α, IL-1β, and IL-6, in the initiation, proliferation, and progression of epithelial ovarian cancer, akin to the observations made in endometriosis." (PMID 38384812, 2024). "Animal studies have demonstrated that gut microbiome plays a crucial pro-inflammatory role in the progression of endometriosis and results in higher levels of IL-1β, TNF-α, IL-6, and TGF-β1 and an increase in macrophages at the lesion site." (PMID 38627726, 2024). "Tumor necrosis factor alpha (TNF-α), a pro-inflammatory cytokine, was consistently reported as increased in larger cohorts of women with endometriosis in two biological compartments: peritoneal fluid, and follicular fluid." (PMID 38341605, 2024). "Studies have reported the presence of significantly higher levels of TNF-α in patients with endometriosis at an early stage of the disease." (PMID 38892003, 2024). "Higher levels of cytokines or chemokines have also been described in patients with endometriosis, including macrophage migration inhibitory factor, TNF-α, IL-1β, IL-6 and IL-8." (PMID 39595086, 2024). "Endometriosis induces systemic inflammation through pro-inflammatory cytokines such as IL-1β, IL-6, and TNF-α." (PMID 39381444, 2024). "TNFRSF1B encodes the TNFα receptor, TNFR2; both TNFR1 and TNFR2 have been investigated as potential biomarkers for endometriosis, given the pro-inflammatory roles of TNFα signaling." (PMID 38402336, 2024). "Elevated TNFα, IL-1β, and IL-6 levels have been reported in the blood, peritoneal fluids, and/or eutopic and ectopic endometrial tissues of women with endometriosis." (PMID 39192982, 2024). "Nuclear factor (NF)-κB, a major regulator of inflammatory response, is activated by various cytokines increased in the peritoneal fluid of women with endometriosis, such as TNF-α and IL-1β." (PMID 37108154, 2023). "In endometriosis lesions, macrophages and mast cells have been found to release chemokines (such as TNF, IL-6, and IL-1 β) that play a key role in the neutrophil recruitment process." (PMID 37138868, 2023).
endometriosis (continued). "Inflammation in endometriosis is driven by elevated levels of macrophages and cytokines, including interleukins (IL-1β, IL-6, IL-8, IL-17), tumor necrosis factor α (TNFα), cyclooxygenase 2 (COX-2), and macrophage inhibitory factor (MIF)." (PMID 37834449, 2023). "These cells are thought to play a significant role in the pathogenesis of endometriosis: TNF-α and IL-1β stimulate ectopic endometrial cells to synthesize histamine-releasing factor (HRF), which is also involved in the pathogenesis of allergy." (PMID 37760889, 2023). "In that regard, increased levels of IL-1β and TNF-α were found in animals subjected to endometriosis and treated with the vehicle compared to the sham." (PMID 36982152, 2023). "High intake of tFAs is associated with higher levels of several inflammatory markers, such as IL-6 and TNF- α, which are thought to be involved in the pathogenesis of endometriosis." (PMID 36983810, 2023). "Curcumin was also found to repress activation of NF-κB induced by TNF-α and IL-1β in endometriosis, with effects such as reduced production of proinflammatory cytokines, chemokines, and cell adhesion molecules." (PMID 36769226, 2023). "TNF-α is produced by M1 macrophages in the peritoneal fluid of women with endometriosis and correlates with lesion number and size." (PMID 37545483, 2023). "Endometriosis promoted acceleration of vasculogenesis and inflammation with the apoptotic pathway by inducing Caspase-3 and TNF-α and MAPK signaling pathways in endometriotic cells." (PMID 37630196, 2023). "The elevated concentrations of crucial pro-inflammatory cytokines, namely IL-1β, IL-6 and TNF-α, have been demonstrated in patients with endometriosis." (PMID 37143676, 2023). "E2 promotes the initial inflammatory mediator, LPS/TLR4, signaling to directly stimulate peritoneal macrophages to secrete TNF-α and IL-6 in the internal milieu of pelvic inflammation within endometriosis." (PMID 37226177, 2023). "In other studies, TNF-α expression was found to be significantly higher in ectopic endometriosis tissue than in eutopic tissue." (PMID 38868448, 2023). "The current findings suggest a new basis for understanding the mechanism of TNFα in the pathogenesis of endometriosis." (PMID 37205467, 2023). "In women with stage 3/4 of endometriosis—according to the revised criteria of the American Society for Reproductive Medicine (ASRM)—TNFα was significantly increased." (PMID 36837548, 2023). "Several cytokines including IL-1β and TNF-α were reported to be increased in the PF of women with endometriosis." (PMID 36982152, 2023). "On molecular level, both suture and inoculation models of endometriosis induced a pro-inflammatory state with increased concentrations of pro-inflammatory cytokines IL-1β and/or TNF-α." (PMID 36844654, 2023). "These microbial imbalances have been correlated with increases in inflammatory markers such as TNF-α and IL-6, both often raised in those with endometriosis." (PMID 38002684, 2023). "On the other hand, thalidomide and pioglitazone, apart from their main mechanisms of action, can also decrease IL-8 secretion by inhibition of NF-κB activation by TNF-α in endometriosis." (PMID 36769226, 2023). "In agreement with our findings, Grandi and co-workers reported that exposure to inflammatory cytokines TNFα and IL1β reduced the expression of PR mRNA and protein expression in the endometrial stromal cells of women with endometriosis." (PMID 37260554, 2023). "The reduction of IL-1β and TNF is conducive to the downregulation of chronic inflammatory processes, which is helpful in the treatment of endometriosis." (PMID 37138868, 2023). "Recent studies have shown that dysregulation of cytokines such as TNF-α, IFN-γ, and IL-97 associated with endometriosis is also an accomplice to infertility." (PMID 37763053, 2023). "The role of TNF-α in stimulating endometrial cell adhesion and inducing angiogenesis is particularly needed in the early stages of the onset of endometriosis." (PMID 38601772, 2023).